RNU6-283P (RNA, U6 small nuclear 283, pseudogene)
Synonyms: RNU6-683P
Gene: Small nuclear RNA gene on chromosome 6 (31,370,134 to 31,370,240, forward strand). Ensembl gene ENSG00000201658.
Homologues: Orthologues: chimpanzee U6 (99% identical), macaque U6 (97% identical), rabbit U6 (92% identical), guinea pig U6 (90% identical). Paralogues in human: RNU6-1145P (92% identical), RNU6-1316P (92% identical), RNU6-20P (91% identical), RNU6-35P (91% identical), RNU6-434P (91% identical), RNU6-25P (90% identical), RNU6-38P (90% identical), RNU6-393P (90% identical), RNU6-41P (90% identical), RNU6-477P (90% identical), RNU6-639P (90% identical), RNU6-698P (90% identical), and 1285 more.